ALB (albumin)
Diseases named in the same sentence as ALB in open-access papers (continued):
Sharing a sentence is not in itself a finding about the gene and the disease.
hepatocellular carcinoma (continued). "GGT/albumin (GAR) is most helpful for prognosis and reflects significant differences in the aggressive characteristics of hepatocellular carcinoma." (PMID 41316810, 2025). "The albumin–bilirubin (ALBI) score, initially developed to quantify liver dysfunction in hepatocellular carcinoma, incorporates two routine laboratory markers—albumin and total bilirubin—and reflects both synthetic and metabolic liver function." (PMID 41153732, 2025). "Many studies have used immortalized hepatocyte cell lines such as hepatocellular carcinoma HepG2 and AML-12 cells; these cell lines present liver-like functions including albumin synthesis and triglyceride secretion." (PMID 38474588, 2024). "Initially recognized as a prognostic factor for hepatocellular carcinoma, the AAPR, calculated from ALB and ALP, has been identified as a prognostic predictor for various cancers." (PMID 39013971, 2024). "As a composite indicator based on fibrinogen and albumin, FAR has been reported to be a potential predictor of adverse outcomes in various malignancies, such as esophageal squamous cell carcinoma, hepatocellular carcinoma, and NSCLC." (PMID 38978733, 2024). "The albumin–bilirubin (ALBI) grade has surfaced as a viable substitute for assessing liver functional reserve in individuals afflicted with hepatocellular carcinoma (HCC)." (PMID 39055134, 2024). "Herein, we report the construction of bovine serum albumin (BSA)–stabilized manganese oxide (MnO2)/semiconducting polymer (SP) nanocomposites for combinational PTT and CDT of hepatic carcinoma in living mouse models." (PMID 35733530, 2022). "The albumin–bilirubin (ALBI) score was created to assess the severity of liver dysfunction and to predict prognosis of hepatocellular carcinoma." (PMID 36050367, 2022). "Albumin–bilirubin (ALBI) grade is an objective and reproducible model for evaluating overall survival (OS) in patients with hepatocellular carcinoma (HCC)." (PMID 36291867, 2022). "A combination of albumin-bilirubin (ALBI) grading and the Prognostic Nutritional Index (PNI) was identified recently as a highly predictive tool for patients with hepatocellular carcinoma (HCC) undergoing tumor ablation." (PMID 34439116, 2021). "CRP and albumin ratio (CAR), as a new inflammation-based prognostic score, has been demonstrated to show prognostic value in hepatocellular carcinoma (HCC), oesophageal squamous-cell carcinoma, and small-cell lung cancer." (PMID 34726101, 2021). "The albumin bilirubin (ALBI) score and model of end stage liver disease (MELD) are prognostic in patients with hepatocellular carcinoma (HCC)." (PMID 34319020, 2021). "The stability, the capacity to bind bovine serum albumin (BSA), the cytotoxicity against human hepatoma cell line, as well as the potential anti-diabetic activity of the four compounds are investigated." (PMID 34067862, 2021). "Several existing prognostic models, including the four-and-seven criteria, six-and-12 score, hepatoma arterial-embolization prognostic (HAP) scores, and albumin-bilirubin grade, have been proposed to predict clinical outcome after TACE." (PMID 32850345, 2020). "Albumin-bilirubin (ALBI) showed its prognostic and predictive value in hepatobiliary disease like hepatocellular carcinoma." (PMID 32664063, 2020). "This work evaluated the prognostic performance of Child-Pugh (CP), albumin-bilirubin (ALBI) and platelet-albumin-bilirubin (PALBI) scores in hepatocellular carcinoma (HCC) patients undergoing radiotherapy (RT)." (PMID 29988960, 2018).
hepatocellular carcinoma (continued). "Targeted deletion of the Nf2 gene in the mouse liver (albumin-Cre driver specific for hepatocytes and biliary cells) led to increased Yap activation, increased cell proliferation, increased liver size and eventual hepatocellular carcinoma (HCC)." (PMID 26932373, 2014). "These two case reports also demonstrate that patients with hepatic carcinoma who experience this rare form of CLS after treatment with IL-11 seem to respond to a therapeutic regimen that involves hydroxyethyl starch, albumin, and diuretic therapy." (PMID 21619578, 2011). "Notably, few reports have explored the role of the albumin‐to‐fibrinogen ratio (AFR) in HNSCC, though the value of AFR as a prognostic indicator has been evaluated in patients with hepatocellular carcinoma, colorectal cancer, and gastric cancer." (PMID 41264384, 2025). "The albumin-to-alkaline phosphatase ratio (AAPR), which is obtained by dividing the serum albumin level by that of serum alkaline phosphatase, was first examined in patients with hepatocellular carcinoma in 2015." (PMID 40095849, 2025). "Even in patients with hepatocellular carcinoma, liver function was good and albumin levels were not decreased." (PMID 38791890, 2024). "Moreover, together with the loss of growth arrest, the previous enhancement of maturation in the hepatoma line was significantly reduced as shown by decreased expression of maturation markers CYP3A4, ALB, AHR, GLUL, and PCK1." (PMID 38037844, 2024). "To test our hypothesis, we used lipotoxic human hepatoma HepG2 cells and mouse hepatocyte AML 12 as cellular models and palmitate complexed with albumin as lipotoxic agent." (PMID 36690274, 2023). "A novel inflammation-related marker, albumin-bilirubin (ALBI) score, calculated from albumin and bilirubin, has been identified for the first time as estimating the degree of liver function in patients with hepatocellular carcinoma." (PMID 37325466, 2023). "A new prognostic index has been introduced that combines serum albumin and serum alkaline phosphatase, i.e., the albumin-to-alkaline phosphatase ratio (AAPR), and has been shown to have significant prognostic value in several types of cancer, especially in hepatocellular carcinoma." (PMID 34885242, 2021). "In one study, dendrimers conjugated with epidermal growth factor (EGF), human serum albumin (HSA) and nimotuzumab antibody (h-R3) were used to deliver siRNA against polo-like kinase-1 (PLK1) to the EGFR-overexpressing hepatocellular carcinoma cell line (HepG2) and tumor-bearing BALB/c nude mice." (PMID 33805602, 2021). "Thus the aim of this study was to evaluate the prognostic value of the new liver function assessment tool, the albumin–bilirubin (ALBI) grade, in patients with hepatocellular carcinoma undergoing TACE." (PMID 31191834, 2019). "In our study, the transduction of helper-free pseudotyped retrovirus, which showed a broad host range, in human hepatoma cells was performed under 2 conditions, that is, in the presence of polymerized human serum albumin (pHSA) and in the absence of pHSA." (PMID 20236514, 2010). "Introduction of AhR into c12, a similar AhR-defective mouse hepatoma cell line, also did not restore albumin expression, and furthermore, did not lead to changes in cellular morphology or cell cycle parameters." (PMID 19936078, 2007). "We introduced an albumin-promoter-driven ICP4 expression cassette into the tk gene locus of d120 and showed that the resultant virus G92A selectively replicated in and killed hepatoma cells and tumor xenografts in which the albumin promoter was active." (PMID 16995942, 2006). "Components and calculation: The albumin-bilirubin (ALBI) score represents a straightforward and objective scoring system utilized to evaluate liver function and prognosticate outcomes for patients with liver disease, particularly hepatocellular carcinoma (HCC)." (PMID 38681340, 2024).
hepatocellular carcinoma (continued). "CRP and albumin may be active mediators of both hepatocellular cancer development and a more aggressive phenotype, rather than merely passive reflections of inflammatory processes." (PMID 36923698, 2023). "In this study, we report the construction of bovine serum albumin (BSA)–stabilized manganese oxide (MnO2)/semiconducting polymer (SP) nanocomposites to combine photothermal therapy (PTT) and chemodynamic therapy (CDT) for treatment of hepatic carcinoma in living mouse models." (PMID 35733530, 2022). "In a hepatocellular carcinoma (HCC) cell line transfected with MTL-CEBPA, increased levels of both CEBPA and albumin mRNA in addition to a 3-fold increase in albumin secretion and 50% decrease in cell proliferation was observed." (PMID 34502076, 2021). "Hepatoma arterial-embolization prognostic (HAP) score, which consists of four tumor-related variables (alpha-fetoprotein [AFP] level and tumor size) and liver function-related variables (serum albumin and total bilirubin levels), has been proposed for predicting outcomes after TACE." (PMID 30991968, 2019). "ALB and GLB are two important components of systemic inflammation, and the combination of these two markers (AGR) has been reported to be significant and validated in several types of cancers, including nasopharyngeal carcinoma, small-cell lung cancer and hepatocellular carcinoma." (PMID 28654895, 2017). "Tumor cells in hepatoid foci resemble the morphology of hepatocellular carcinoma (HCC), and immunohistochemically can be positive for AFP, alpha-1 antitrypsin (AAT), alpha-1 antichymotrypsin (ACT) and albumin (ALB)." (PMID 20062620, 2009). "The albumin–bilirubin (ALBI) grade is a novel index developed to assess the liver function and predict the prognosis in patients with hepatocellular carcinoma (HCC), independent of the degree of underlying liver fibrosis." (PMID 39590135, 2024). "Elevated preoperative γ-glutamyl transferase (GGT) levels or reduced serum albumin levels have been established as negative prognostic factors for patients with hepatocellular carcinoma (HCC) and various other tumors." (PMID 38799149, 2024). "The albumin–bilirubin (ALBI) score, initially introduced through an international collaboration, was designed to evaluate liver function in hepatocellular carcinoma (HCC) patients." (PMID 37998586, 2023). "This study tended to examine the association between preoperative albumin–bilirubin (ALBI) grades and the incidence of achieving or not achieving TO (non-TO) in patients with hepatocellular carcinoma (HCC) undergoing laparoscopic hepatectomy." (PMID 35965571, 2022). "In addition, albumin-bilirubin (ALBI) score, which used to assess the severity of liver dysfunction in hepatocellular carcinoma (HCC) patients, was developed to evaluate the prognosis of ACLF patients lately." (PMID 34911462, 2021). "Factors influencing the survival of hepatocellular carcinoma (HCC) patients include portal vein thrombosis (PVT), tumor numbers (multifocality), blood alpha-fetoprotein (AFP) levels, and the degree of liver damage (levels of blood bilirubin and albumin)." (PMID 33546234, 2021). "The combination of the albumin-bilirubin (ALBI) grading and the Prognostic Nutritional Index (PNI) offers potential as a highly predictive tool for patients with hepatocellular carcinoma (HCC)." (PMID 34439116, 2021). "We evaluated the ability of various grading scales including platelet-albumin-bilirubin (PALBI) and albumin-bilirubin (ALBI) grades to predict overall survival (OS) according to treatment modality in patients with hepatocellular carcinoma (HCC)." (PMID 31048923, 2019). "HepaRG cells, in contrast to the widely used Huh7 and HepG2 hepatoma cell lines, are non-transformed cells, and their metabolism closely resembles that of normal primary hepatocytes, characterized by a strong secretory activity (albumin) and secretion of vLDL (apoB ELISA)." (PMID 30567412, 2018).
hepatocellular carcinoma (continued). "The albumin–bilirubin (ALBI) grade, a validated prognostic tool in cancers such as hepatocellular carcinoma, has not been evaluated in acute respiratory distress syndrome (ARDS)." (PMID 40692980, 2025). "The plasma AT-III level was significantly lower in patients with liver failure-related death than in those with hepatocellular carcinoma (HCC)-related death (p = 0.005), although the Child–Pugh and albumin-bilirubin (ALBI) scores were not significantly different between these two groups." (PMID 37175438, 2023). "The purpose of this study was to develop and validate a nomogram integrating the albumin-bilirubin (ALBI) and serum γ-glutamyl transpeptidase (GGT) level to predict postoperative overall survival (OS) and disease-free survival (DFS) of hepatocellular carcinoma (HCC)." (PMID 31598154, 2019). "The albumin-to-alkaline phosphatase ratio (AAPR), which has recently been proved to be a significantly prognostic predictor for hepatocellular carcinoma and metastatic nasopharyngeal carcinoma, but it has not yet been studied in UTUC patients." (PMID 30120312, 2018). "In 2 of 13 cells, the PTP4A3/PRL-3 mRNA levels were lower than in the known cell lines such as HLE and HLF derived from epithelial and fibroblastic colonies in cultures of the same undifferentiated hepatomas and did not produce AFP and albumin." (PMID 23064776, 2013). "Additionally, the albumin level after NG and ND treatment in EGFP-expressing hepatoma cells was higher with respect to nontransduced cells." (PMID 25816103, 2015).
pneumonia (296 papers, 2006 to 2026). An acute, acute and chronic, or chronic inflammation focally or diffusely affecting the lung parenchyma, caused by an infection in one or both of the lungs (by bacteria, viruses, fungi, or mycoplasma.). "Pneumonia occurred in 24 patients and was independently associated with older age (OR 1.055, p = 0.012) and lower serum albumin levels (OR 0.915, p = 0.047)." (PMID 42221094, 2026). "The Prognostic Nutritional Index, based on serum albumin and lymphocyte count, has previously been associated with mortality in pneumonia cohorts." (PMID 41597493, 2026). "The subgroup analyses further revealed that the risk of developing pneumonia was more pronounced in younger, female, and healthier patients at lower preoperative albumin levels." (PMID 41200138, 2025). "A single-center retrospective cohort study found that a higher Urea-to-Albumin Ratio at the onset of ICU admission is independently associated with increased in-hospital mortality in patients with severe pneumonia." (PMID 40547131, 2025). "In this retrospective study, we analyzed data from non-cardiac surgical patients to determine the association between preoperative albumin levels and postoperative in-hospital pneumonia." (PMID 41200138, 2025). "A correlation was identified between the risk of pneumonia and preoperative laboratory parameters, including lower hemoglobin, albumin, and lymphocyte levels, as well as higher LDH levels." (PMID 39857079, 2025). "In our study on age-stratified albumin-based inflammatory ratios for severe pneumonia risk prediction in children, models like NPAR (1–6 years) and CAR (7–12 years) achieved NPVs of 88.0%, 85.9%, and 83.0% across different age groups." (PMID 41321450, 2025). "If aspiration was confirmed on VFSS, low nutritional status—defined by an albumin level below 3.5 g/dL—was associated with a 62.50% (n = 5) pneumonia risk, whereas an albumin level of 3.5 g/dL or higher indicated a 10.0% (n = 5) risk." (PMID 41346384, 2025). "Low albumin and low gamma gap levels were strongly associated for pneumonia death (HR = 12.4, 3.98–38.5)." (PMID 41248155, 2025). "The interaction between albumin and gamma gap levels was significant for deaths from all-causes, pneumonia and other-causes." (PMID 41248155, 2025). "Several studies have highlighted the association between low blood albumin concentration and poor prognosis in pneumonia, sepsis, and cancer." (PMID 40346545, 2025). "A 1 g/L increase in preoperative albumin levels was associated with a 4.4% reduction in adjusted odds ratio (aOR) of postoperative pneumonia (aOR: 0.956, 95% CI: 0.940–0.973, p < 0.001)." (PMID 41200138, 2025). "P-values for interaction were statistically significant between low albumin and high gamma gap groups for death from all-causes (p = 0.003) and other-causes (p = 0.010) and between low albumin and low gamma gap groups for pneumonia death (p = 0.004)." (PMID 41248155, 2025). "Some studies have suggested that serum albumin was associated with mortality in patients with pneumonia." (PMID 41085005, 2025). "As an indicator of nutritional status, serum ALB has been associated with the risk of progressive disease among patients with pneumonia." (PMID 40831793, 2025). "Multivariate logistic regression analysis identified pneumonia, external ventricular drainage, tracheotomy, procalcitonin, C-reactive protein, and albumin levels as independent risk factors for intracranial infections (p < 0.05)." (PMID 40529435, 2025). "Postoperative albumin emerges as an independent risk factor for the development of postoperative pneumonia." (PMID 39776439, 2024). "High levels of albumin have been associated with an increased risk of complications and mortality in pneumonia patients." (PMID 39202004, 2024). "Pneumonia occurred at 4 [2–7.5] postoperative days; further, it was associated with lower preoperative serum albumin levels, a longer anesthesia duration, and recurrent nerve palsy." (PMID 38238681, 2024).